C3 (complement C3)
Diseases named in the same sentence as C3 in open-access papers (continued):
Sharing a sentence is not in itself a finding about the gene and the disease.
glomerulosclerosis (continued). "To minimize the risk of inclusion biases despite the lack of electron microscopy, we excluded patients with incomplete renal immunostaining or with glomerular C3 deposits outside glomerulosclerosis lesions." (PMID 30832362, 2019). "All had microscopic haematuria or polyclonal IgM/C3 mesangial deposits in the glomerulosclerosis area, thus confirming the diagnosis of primitive FSGS in these patients." (PMID 30832362, 2019). "Kidney biopsy showed pronounced glomerular sclerosis, mesangial proliferation, and distinct C3 staining with little immunoglobulin deposition." (PMID 29329521, 2018). "This was illustrated by less complement C3 deposits, diffuse proliferative glomerular lesions and glomerulosclerosis." (PMID 28584258, 2017). "Although FSGS is not considered a “classic” immune-complex glomerulonephritis, glomerular IgM and C3 are frequently observed in areas of glomerular sclerosis, and the deposition of C4 fragments in the glomeruli of patients with FSGS has been reported." (PMID 26335102, 2015). "Despite these limitations, we showed that although there were no statistically significant histological changes attributable to IgM and/or C3 deposition, such patients did have higher rates of segmental and global glomerulosclerosis coupled with a higher level of proteinuria and serum creatinine." (PMID 37182061, 2023). "In conclusion, this study retrospectively compared the clinicopathological features and outcomes between the low C3 group and the normal C3 group, and found that patients with low serum C3 levels had a higher proportion of glomerular sclerosis progressing into kidney failure." (PMID 35874697, 2022). "Furthermore, renal biopsy findings showed a higher proportion of global glomerulosclerosis (9.5 vs. 4.3%, p < 0.001) and a higher deposition rate of C3 (89.1 vs. 82.9%, p = 0.013) in IgAN with the arteriolar hyalinosis group." (PMID 35658824, 2022). "Notably, C3 gene expression was significantly upregulated in both glomeruli and tubules, with the increase in glomerular C3 showing a strong correlation with the degree of glomerulosclerosis." (PMID 34806406, 2022). "We found that the quantity of urine protein was strongly correlated with the incidence of intraglomerular C3 deposition (r = 0.293, p = 0.007), degree of tubular atrophy (Ct, r = 0.289, p = 0.008), glomerular sclerosis (Cg, r = 0.238, p = 0.009), and interstitial fibrosis (Ci, r = 0.227, p = 0.038)." (PMID 22586485, 2012). "WT+BSA mice showed podocyte depletion accompanied by glomerular complement C3 and C3a deposits, PEC migration to capillary tuft, proliferation, and glomerulosclerosis." (PMID 27345360, 2016). "Interestingly, glomerulosclerosis showed a significant positive correlation with 15 proteins, including SAA4 (= 0.346) and C3 (= 0.435)." (PMID 39835101, 2024).
rheumatoid arthritis (37 papers, 2007 to 2025). A chronic, systemic autoimmune disorder characterized by inflammation in the synovial membranes and articular surfaces. "In consequence, C3 or CD46‐deficient patients suffer from recurrent infections while dysregulation of CD46 signaling contributes to Th1 hyperactivity in rheumatoid arthritis and multiple sclerosis." (PMID 28444759, 2017). "Beyond these cases, a sixty-year-old female with rheumatoid arthritis developed purpura and hematuria while receiving etanercept; both skin and kidney biopsies showed IgA and C3 deposition diagnostic of HSP." (PMID 27529048, 2016). "In rheumatoid arthritis patients treated for 12 months with tocilizumab, an anti-interleukin-6 receptor monoclonal antibody that rapidly reduces acute phase reactants, C3 and C4 serum levels also decrease." (PMID 36983904, 2023). "For examples, levels of plasma C3 are significantly elevated in patients with rheumatoid arthritis and axial spondyloarthritis." (PMID 34722636, 2021). "Our analysis revealed significantly higher IgG reactivity against the citrullinated fibrinogen β and filaggrin peptides as well as an IgA reactivity that was exclusive for citrullinated fibrinogen β peptide and C3 deposition in rheumatoid arthritis patients." (PMID 24797804, 2014). "Significant reduction in circulation complement (C3) was found in 43 rheumatoid arthritis patients treated with PNS for 28 days, and which was associated with improved clinical symptoms such as joint swelling index when compared to the control subjects." (PMID 25620952, 2014). "Specific peptidic fragments were differentially excreted between groups; fragments of protein S100-A9 and gelsolin were less abundant in rheumatoid arthritis while fragments of uromodulin, complement C3 and fibrinogen were all increasingly excreted." (PMID 25144639, 2014). "In addition, CXCL12 was enriched in rheumatoid arthritis (hsa05323), and C3 was enriched in leishmaniasis (hsa05140)." (PMID 36398072, 2022). "However, serum levels of C4, and more specifically C3, are elevated in serum of patients with rheumatoid arthritis." (PMID 24489446, 2013). "We have tested, in a mouse model of rheumatoid arthritis, whether C3 synthesized within the synovium is important in promoting inflammation." (PMID 17763447, 2007). "Similarly, elevated C3 mRNA expression in synovial T cells of patients with rheumatoid arthritis correlates with disease severity, and excessive CD46 signaling, the surface receptor engaged by intracellularly processed C3, is a pathogenic driver of hyperinflammation at this site." (PMID 40519170, 2025). "Conversely, uncontrolled intracellular C3 activation leads to dysregulation of CD46-mediated stimulation of human T cells and contributes to pathologically hyperactive Th1 responses in rheumatoid arthritis (RA)." (PMID 28149297, 2017). "Conversely, uncontrolled intracellular C3 activation and CD46 signalling leads to the dysregulation of human T cell responses and contributes to pathologically hyperactive TH1 cells in autoimmune disease (e.g., rheumatoid arthritis (RA))." (PMID 35860237, 2022). "CXCL12, C3, FN1, COL1A2, ACTB, VCAM1, and MMP2 were identified and finally verified as the hub genes, mainly enriched in pathways like leukocyte transendothelial migration, PI3K-Akt signaling pathway, viral myocarditis, rheumatoid arthritis, and platelet activation." (PMID 36398072, 2022). "In addition, “bone inflammation disease” and “rheumatoid arthritis” ontologies were highly enriched in C3 regions, confirming that C3 regions represent an RA signature, for example, IL-1B and JAK1, which are essential for proinflammatory signal transduction and upregulated in RA patients." (PMID 33863328, 2021).
Cognitive impairment (36 papers, 2014 to 2026). Abnormal cognition is characterized by deficits in thinking, reasoning, or remembering. "Collectively, these findings demonstrate that perioperative serum C3 changes are associated with postoperative cognitive impairment, with the potential to predict POCD." (PMID 41221556, 2026). "Changes in serum C3 during the perioperative period are associated with postoperative cognitive impairment in surgical patients, with potential for predicting POCD." (PMID 41221556, 2026). "Blocking the C3-C3aR axis can improve microglial phagocytosis, thus rescuing synapse loss and cognitive impairment in infected mice." (PMID 40294039, 2025). "In the App NL-G-F mouse animal model, the OMVs caused cognitive impairment and memory loss through the inhibition of the C3-C3aR signaling pathway." (PMID 39942791, 2025). "C3 deficiency reportedly prevents age‐related synaptic and neuronal loss in specific brain regions and protects against cognitive impairment in aging C57BL/6 mice." (PMID 40539508, 2025). "Complement C3, the central complement component, has been implicated in synaptic loss and cognitive impairment." (PMID 38427092, 2024). "In AD mice and multiple sclerosis models, microglia can induce synaptic loss and cognitive impairment through C1q-C3 signaling axis-mediated synaptic phagocytosis." (PMID 37650573, 2023). "Another study indicated that gene knockout or inhibition of the C3/C3R signaling system reduced the abnormal phagocytosis of synapses by microglia and delayed the process of virus‐induced synapse loss and cognitive impairment." (PMID 37177836, 2023). "Intraperitoneal administration of LPS (10 mg/kg) for 7 days induces marked upregulation of C1q and C3 by activating the classical complement pathway, microglial activation, synapse loss in the hippocampus, and cognitive deficits in Kunming mice." (PMID 32391019, 2020). "C3 deficiency ameliorates age-dependent loss of synapses and neurons, and cognitive deficits in aged APP/PS1 mice although it increases cerebral Aβ deposits." (PMID 32391019, 2020). "Finally, perioperative changes in serum C3 in surgical patients were found to be linked to postoperative cognitive impairment." (PMID 41221556, 2026). "While germline C3-deficiency protected against cognitive impairment in the Water T-Maze and Contextual Fear Conditioning, C3iKO and C3KO mice performed better on the Spatial Novelty Y-Maze and Novel- and Displaced- Object Recognition tasks in this current study." (PMID 40678242, 2025). "Furthermore, captopril treatment reduced complement C3 production in astrocytes while inhibiting C3–C3ar signaling-mediated glial activation, potentially preventing synaptic loss, epileptogenesis, and cognitive impairment." (PMID 36104755, 2022). "We hypothesized that levels of C3 and associated factor H (FH) can potentially distinguish between mild cognitive impairment (MCI) and dementia stages of AD, but we also found their levels to be influenced by age and disease status." (PMID 26887322, 2016). "Activity in the complement cascade in individuals with HIV-1 has previously been studied in context of HIV-associated cognitive impairments; previous studies found elevated protein expression of complement component 3 (C3) in patients diagnosed with HIV-associated dementia." (PMID 27378953, 2016). "Previously, we found that C3/C3aR (an “eat me” signal) could regulate microglial phagocytic activity and administration of C3aR antagonist could alleviate surgery-induced synapse loss and cognitive impairment in PND mice." (PMID 35360151, 2022). "Collectively, these results demonstrate that inhibition of liver‐derived C3 can ameliorate cognitive impairment induced by anesthesia/surgery, displaying that hepatogenous C3 contributes to the impairment of cognitive function." (PMID 41221556, 2026).
Cognitive impairment (continued). "We identified liver‐derived blood proteins C3, HP, ITIH4, and SAA1 as the candidate molecules associated with cognitive impairment based on the proteomics of mouse liver and blood, as well as the transcriptomic and proteomic profiles of human organs." (PMID 41221556, 2026). "Inhibiting hepatogenous C3 is demonstrated to salvage the anesthesia/surgery‐induced cognitive impairment, structural and functional injury of synapse, and C3aR‐mediated microglial phagocytosis." (PMID 41221556, 2026). "In patients with T2DM, serum C3 levels were higher in those with mild cognitive impairment, showing a U-shaped correlation with low-density lipoprotein-cholesterol (LDL-C) levels." (PMID 41016959, 2025). "By knocking the complement C3-C3aR axis, synaptic damage and cognitive impairment in S. aureus-infected mice were rescued." (PMID 40294039, 2025). "The OMVs from H. pylori have the ability to increase interactions between astrocytes and microglia via C3-C3aR, and the microglial activation triggers neuronal dysfunction and Aβ deposition, resulting in cognitive impairment." (PMID 39942791, 2025). "We noticed that cytokines IL-1β, TNF-α and IL-6 changes were rapid but transient, while C3 upregulation was delayed but prolonged, a pattern that concur more with the time course of cognitive deficits." (PMID 38427092, 2024). "In this study, we found that there were significant differences between patients with cognitive impairment only, T2DM, or T2DM with cognitive impairment in the levels of the complement proteins C1q, C3, C3b and the complement regulatory protein FH." (PMID 35370615, 2022). "Activation of NLRP3 inflammasome in microglia was then shown to play an important role in EAE cognitive deficits via the alteration of astrocyte phenotypes and the release of complement component 3 (C3)." (PMID 35563859, 2022). "Higher serum levels of C1q, C3 and FH in the cognitive impairment only group indicate that activation of the classical pathway and inhibition of the alternative pathway underlie the neuronal damage within this group." (PMID 35370615, 2022). "In a small non-randomized clinical study, Posiphen was found to reduce inflammatory markers (i.e., MCP-1, Complement C3) in the CSF of patients with mild cognitive impairment." (PMID 32058974, 2020). "Using xMAP® technology based assays we measured complement 3 (C3) and factor H (FH) in the CSF of 110 controls (CN), 187 mild cognitive impairment (MCI) and 92 AD subjects of the AD Neuroimaging Initiative (ADNI) at baseline." (PMID 25478014, 2014). "Furthermore, we demonstrated that inhibition of hepatogenous C3 rescued anesthesia/surgery‐induced cognitive impairment, structural and functional injury of synapse, and C3aR‐mediated microglial phagocytosis." (PMID 41221556, 2026). "Inhibition of hepatogenic C3 rescues anesthesia/surgery‐induced cognitive impairment, structural and functional injury of synapse, and C3aR‐mediated microglial phagocytosis, highlighting peripheral C3 as a promising target for the prevention and therapy of cognitive impairment." (PMID 41221556, 2026). "Some genes (C3, C1QA) about complement cascade play an important role in synapse refinement during brain development, but aberrant upregulation and deposition of complement will lead to synapse loss and cognitive impairment." (PMID 37333458, 2023). "Surgery-induced activation of complement component 3/complement component 3 receptor (C3/C3R) signaling pathway, which is later regarded as the most characteristic marker of neurotoxic astrocytes, is reported to worsen cognitive impairments in perioperative neurocognitive disorders." (PMID 37170230, 2023). "Under these conditions, microglial cells also displayed a high level of expression of the gene coding for complement C3 that directly affects the integrity and function of neurons in relation with the establishment of cognitive disorders and the development of Tau pathology." (PMID 36539803, 2022).
Cognitive impairment (continued). "This prompted us to investigate whether blockage of soluble C1q and C3 by i.c.v. infusion of specific antibodies affected ZIKV-induced cognitive impairment." (PMID 31488835, 2019). "We next aimed to identify the injury-induced cellular and molecular changes that lead to chronic cognitive deficits in aged animals, and measured increases in complement initiation components C1q, C3, and CR3, which are known to regulate microglial–synapse interactions." (PMID 30486287, 2018). "On the one hand, microglia-derived C1q could induce neuron loss and chronic neuroinflammation, thereby leading to abnormal sleep spindles and epileptic spikes after TBI; on the other hand, C3 opsonin triggered microglial phagocytosis of synapses and chronic cognitive deficits." (PMID 36815939, 2023). "Because discrepant findings related to C3 and FH resulted from preferential analysis of early (mild cognitive impairment, MCI) or late (dementia) AD stages, we hypothesized that C3 and FH levels were altered (in keeping with complement activation) during the transition from MCI to dementia in AD." (PMID 26887322, 2016). "This surgical dual factors ultimately drove C3 to cross the damaged BBB and selectively colocalize with C3aR in the hippocampus, which results in structural and functional injury of synapse, C3aR‐mediated microglial phagocytosis, and cognitive impairment." (PMID 41221556, 2026). "The reduced synapses, increased complement activation, enhanced microglial phagocytosis, and cognitive impairment were all alleviated in mice lacking C3, the C3a receptor, or with astrocyte-specific C3 gene deletion, compared to WT controls." (PMID 40294039, 2025). "Finally, we found that the inhibition of C3/C3aR by an antagonist (SB 290157) improved the hydrocephalus and cognitive deficits induced by GMH-IVH, indicating that C3/C3aR was a novel and potential therapeutic target for PHH after GMH-IVH." (PMID 39248058, 2025). "We conducted a cross-sectional study to prospectively determine the specific complement activating pathway, which includes different complement proteins (C1q, C3, C3b, C4, FH), in the pathology of T2DM only, cognitive impairment only, and T2DM combined with cognitive impairment." (PMID 35370615, 2022). "However, a recent study showed a lower plasma complement C3 level in amnestic mild cognitive impairment compared to normal." (PMID 30250409, 2018). "Similarly, transthyretin was identified in AD and mild cognitive impairment CSF62 and in our OPLS-DA analysis; serum amyloid A4 protein contributed to variance in our OPLS-DA analysis; complement component C3, however, was not included on our panel." (PMID 27845782, 2016).